MLKL (mixed lineage kinase domain like pseudokinase)
Diseases named in the same sentence as MLKL in open-access papers (continued):
Sharing a sentence is not in itself a finding about the gene and the disease.
melanoma (continued). "Therefore, even when RIPK3 and MLKL are normally expressed, TAK1 can still prevent melanoma cell death." (PMID 40497999, 2025). "With the manipulation of upstream RIPK1 and the effector protein of MLKL in the necroptosis pathway, the relevance of necroptosis to melanoma progression and metastasis is not clear." (PMID 38336727, 2024). "In melanoma cells actively engaged in melanogenesis, the use of melanin synthesis inhibitors to induce depigmentation has shown to restore sensitivity to RIPK1/RIPK3/MLKL-mediated necroptosis." (PMID 38036577, 2023). "Finally, six LLPS-related genes (MLKL, PARVA, PKP1, PSME1, RNF114, and TROAP) constitute the prognostic model and predicted clinical outcomes in melanoma patients." (PMID 37127623, 2023). "Unlike MLKL the necroptosis-regulator RIPK3 does not seem to have any impact on melanoma progression in this model." (PMID 35422482, 2022). "In our model, MLKL was still detectable in the primary tumor, which suggests no major downregulation during melanoma development in this model." (PMID 35422482, 2022). "The viability of melanoma cells depigmented with 10−3 M d-pen, 6 μg/mL KA, or 30 μg/mL KA increased after CV stimulation when the RIPK1, RIPK3, and MLKL kinases were inhibited." (PMID 34072104, 2021). "Our data suggest that loss of RIPK3 in melanoma and selective inhibition of the RIPK3/MLKL axis by BRAF inhibitor Dabrafenib, but not Vemurafenib, is critical to protect from necroptosis." (PMID 26355347, 2015). "In line with the recent report, Dabrafenib but not Vemurafenib blocked necroptosis (black bars) and MLKL phosphorylation, but also protected from DL/IAP antagonist-mediated apoptosis (grey bars) in RIPK3-reconstituted A375 or IGR melanoma cells." (PMID 26355347, 2015). "Indeed, while tumor cell lysates isolated from in vivo growing B16 melanomas showed strong RIPK3 expression, short-term tumor cell culture and in particular prolonged in vitro passaging resulted in rapid loss of RIPK3 but not MLKL protein expression." (PMID 40345706, 2025). "The CV extract has been also reported to induce RIPK1/RIPK3/MLKL-mediated necroptosis in non-pigmented melanoma cells and depigmented (with suppressed melanogenesis) melanoma cells, since co-treatment of the cells with necroptosis inhibitors abrogated the CV-induced cell death." (PMID 36902290, 2023). "It is not clear whether the role of MLKL is sex-dependent or dependent on the speed of melanoma progression." (PMID 35422482, 2022). "Reactivation of the RIPK1/RIPK3/MLKL signalling platform by RIPK3 reconstitution can overcome necroptosis resistance in melanoma and therefore could be used as potential death-inducing targeted therapy against melanoma." (PMID 26355347, 2015). "Interestingly, RIPK3-expressing melanoma cells, but not RIPK3-KD cells, show spontaneous and increased MLKL phosphorylation, a strong indication that kinase activity of RIPK3 is the missing link for DL-mediated necroptosis in melanomas." (PMID 26355347, 2015). "MLKL phosphorylation was detected in a time-dependent manner within 90 min, with further increase up to 6 h after stimulation in RIPK3-expressing, but not in RIPK3-KD or vector control melanoma cells." (PMID 26355347, 2015).
Sepsis (30 papers, 2014 to 2026). Sepsis is defined as life-threatening organ dysfunction caused by a dysregulated host response to infection. "Previous reports suggest that circulating concentrations immunoreactive RIP1, RIP3, and MLKL, assessed by commercially validated ELISA kits, are associated with increased inflammation in lung injury and sepsis." (PMID 33616081, 2021). "Recent studies examining the necroptosis regulators of RIPK1, RIPK3, and MLKL in patients with sepsis reported that their levels were associated with disease severity and/or mortality." (PMID 32492832, 2020). "In line, we found a strong correlation of serum MLKL concentrations and serum lactate concentrations in our cohort of patients, supporting a link between MLKL and sepsis-associated organ failure." (PMID 29606984, 2018). "Sepsis, where emergency hematopoiesis is an essential determinant in survival, is an interesting and highly evolutionarily important avenue of exploration for the study of MLKL S132P polymorphism frequency." (PMID 37770424, 2023). "We report that BM-derived megakaryocytes and blood platelets both express TLR4 on their surface, as assessed via flow cytometry, prompting us to assess the effect of loss of Caspase-8 and MLKL on platelet production and clearance in an in vivo LPS-induced sepsis model." (PMID 33510145, 2021). "Necroptosis effector genes are markedly upregulated with increased RIPK1, RIPK3, and MLKL co-expression evident in spinal GABAergic neurons, while administration of the necroptosis inhibitor Necrostatin-1 substantially preserves neurons and reverses sepsis-associated cardiac functional changes." (PMID 40692211, 2025). "In summary, ECG protects sepsis induced ALI mice by inhibiting necroptosis mediated by the ZBP1/MLKL/RIPK1 signaling pathway." (PMID 41496909, 2025). "The key mediators of necroptosis, such as receptor-interacting protein kinase 3 (RIPK3) and mixed lineage kinase domain-like protein (MLKL), are upregulated in sepsis and contribute to organ damage and mortality." (PMID 40861493, 2025). "In models of skin infection or sepsis, MLKL knock-out mice exhibited high bacterial loads, underscoring the importance of MLKL in host defense." (PMID 39001897, 2024). "In summary, the inhibition of necroptosis mediated by the RIPK1/RIPK3/MLKL signaling pathway confers protective effects in the context of sepsis." (PMID 39544947, 2024). "In the LPS-induced sepsis model, inhibition of MLKL activity with necrosulfonamide (NSA) markedly attenuated necroptosis." (PMID 38161332, 2023). "NSA is not specific for GSDMD even though it has been demonstrated to reduce pyroptosis in a sepsis model since it can also prevent the creation of mixed lineage kinase domain-like protein (MLKL) pore-related to necrosis." (PMID 36713841, 2023). "We found significantly higher expression of RIPK1, RIPK3, and MLKL in the peripheral blood nucleated cells of sepsis patients than controls." (PMID 36765040, 2023). "Western blotting demonstrated that STING and necroptotic signalling were remarkably increased in sepsis and there was a positive correlation between p‐MLKL and p‐STING." (PMID 37475188, 2023). "In an LPS-induced septic piglet model, inhibition of RIPK1 attenuated intestinal epithelial injury, accompanied by an increase in the level of MLKL phosphorylation, suggesting that necroptosis affects intestinal epithelial cell death during sepsis." (PMID 37090690, 2023). "Additionally, clinical studies have shown associations between the levels of necroptosis mediators, including receptor‐interacting kinase 1, RIPK3 and MLKL, and the severity and outcomes of sepsis." (PMID 40318009, 2025). "Furthermore, the plasma levels of necroptosis mediators, including high‐mobility group box‐1 (HMGB1), receptor‐interacting kinase 3 (RIPK3) and mixed‐lineage kinase domain‐like (MLKL) proteins, were well correlated with the severity and mortality in sepsis." (PMID 40318009, 2025).
Sepsis (continued). "We then constructed a batch of sepsis models using MLKL-KO mice." (PMID 40430756, 2025). "In clinical settings, the plasma levels of HMGB-1 were associated with the severity and mortality attributed to sepsis and correlated with RIPK3 (receptor interacting protein kinase 3) and MLKL (mixed lineage kinase domain-like protein), suggesting an association of HMGB-1 with necroptosis." (PMID 36005726, 2022). "We asked whether lung RIPK3 and MLKL expression are elevated following systemic LPS, which induces a systemic inflammatory state relevant to human sepsis and trauma, and whether plasma RIPK3 shows a concomitant rise." (PMID 31253195, 2019). "In this paper, we demonstrate that alterations in MLKL serum levels might be used as a biomarker for patients with critical illness and sepsis, raising the question to the source of MLKL in patients' serum." (PMID 29606984, 2018). "We next analyzed the potential influence of sepsis on MLKL concentrations." (PMID 29606984, 2018). "MLKL as the key driver of necroptotic cell death might therefore represent an important regulator of sepsis as the most severe consequence of bacterial infections." (PMID 29606984, 2018). "Additionally, RIPK3 and MLKL gene expression in circulating leukocytes has been positively correlated with sepsis-related mortality, further emphasizing the role of necroptosis in sepsis-induced lung injury." (PMID 40335920, 2025). "Furthermore, we generated the first adrenocortical MLKL-specific knockout mouse model and revealed that MLKL knockdown significantly ameliorates sepsis-induced adrenal dysfunction in mice, suggesting that necroptosis is the primary mechanism of adrenocortical cell death during sepsis." (PMID 40430756, 2025). "Thus, alterations of circulating MLKL might reflect complex immunological mechanism in sepsis or infectious diseases." (PMID 29606984, 2018). "In sepsis, DLL4+ neutrophils increase in the blood and lungs, upregulating ZBP1, cleaved gasdermin D, cleaved caspase-3, and phosphorylated MLKL, all of which are markers of PANoptosis, exacerbating ALI." (PMID 41392977, 2025). "In sepsis-AKI, RIPK3 aggravated kidney injury in a MLKL-independent manner by promoting mitochondrial dysfunction via NOX4 upregulation, but the contribution of tubular cell death was not clearly demonstrated." (PMID 38077379, 2023). "MLKL concentrations were elevated in adult patients with sepsis and SIRS compared to other groups; however, no significant group-wise differences in MLKL levels were observed in the pediatric cohort." (PMID 40722817, 2025). "Furthermore, in LPS-induced sepsis models, the administration of Necrosulfonamide (NSA) to inhibit MLKL activity effectively suppressed necroptosis." (PMID 39544947, 2024). "Excellent correlations between mtDNA level and necroptosis mediators (RIPK3, MLKL, and HMGB1) in this study show that a large proportion of plasma mtDNA may be released by necroptosis in sepsis." (PMID 36289650, 2022). "Furthermore, the mtDNA copy number showed excellent correlations with those of necroptosis mediators, including RIPK3, MLKL, and HMGB1, which implies a link between plasma mtDNA and necroptosis in sepsis." (PMID 36289650, 2022). "At ICU admission, MLKL serum concentrations were independent of disease severity, presence of sepsis, and etiology of critical illness." (PMID 29606984, 2018). "Furthermore, PPAR-γ activation reduces myocardial expression of the RIP1/RIP3 necrosome complex and its downstream effector MLKL, suggesting that repression of necroptosis by PPAR-γ activation contributes to the improvement of myocardial function in sepsis." (PMID 28845215, 2017). "Furthermore, in the plasma mitochondrial DNA, a potent DAMP, the copy number was highly correlated with the essential necroptosis mediators, including RIPK3, MLKL and HMGB1, suggesting that mitochondrial DNA propagates necroptosis and increases the mortality rate due to sepsis in our previous study." (PMID 40318009, 2025).
Sepsis (continued). "Our research results demonstrate that ECG alleviates sepsis-induced ALI by inhibiting the NLRP3/Caspase-1/GSDMD signaling pathway-mediated pyroptosis, the Bcl-2/Bax/Caspase-3 signaling pathway-mediated apoptosis, and regulating the ZBP1/MLKL/RIPK1 signaling pathway-mediated necroptosis." (PMID 41496909, 2025). "In addition, the markers of necroptosis RIPK1, RIRK3, and MLKL and the HMGB1 released by necroptosis in peripheral blood of septic patients were significantly increased and positively correlated with the severity and mortality attributed to sepsis." (PMID 38816685, 2024). "In our study, serum levels of MLKL correlated with those of other proinflammatory cytokines such as TNF and suPAR, highlighting that elevated levels of MLKL might reflect the activation of immunological processes during sepsis disease." (PMID 29606984, 2018). "Subsequent research has focused more on differences in indicators such as RIPK3 and MLKL, but this does not necessarily indicate that inhibition of RIPK1 is ineffective in treating sepsis." (PMID 37090690, 2023). "In the same vein, this study also showed that plasma RIPK3, MLKL, and HMGB1 levels were significantly higher in non-survivors than in survivors among critically ill patients with sepsis." (PMID 36289650, 2022). "Additionally, in experimental sepsis, where inflammation plays a key role, RIPK3, but not MLKL." (PMID 38077379, 2023).
colon carcinoma (28 papers, 2016 to 2025). "Furthermore, low expression of MLKL was associated with reduced overall survival in colon cancer patients after surgery." (PMID 36170029, 2022). "Interestingly, high levels of phosphorylated MLKL are associated with reduced survival in esophageal and colon cancer patients." (PMID 32561755, 2020). "Finally, we found that high levels of phosphorylated MLKL in human esophageal and colon cancers are associated with poor overall survival." (PMID 26959742, 2016). "For instance, diminished MLKL expression have been documented in ovarian-, cervical-, gastric- and colon cancers, correlating with poor overall survival." (PMID 40691738, 2025). "Resibufogenine, a naturally occurring bioactive compound extracted from toad venom, has been shown to inhibit the growth and metastasis of colon cancer via triggering RIPK3/MLKL-dependent necroptosis in both in vitro and in vivo colon cancer models." (PMID 36361505, 2022). "For example, downregulation of MLKL levels implies poor prognosis in ovarian and colon cancer, while increased expression levels of RIP1 confers a worse prognosis in glioblastoma." (PMID 35560794, 2022). "Colon cancer cells overexpressing GLTP (HT-29) exhibit RIPK-3-mediated MLKL phosphorylation, increased intracellular Ca2+, levels and induce cell death through necroptosis." (PMID 36685937, 2022). "When rectal cancers cases were examined independently from colon cancers cases in the TCGA, the median gene expression value for MLKL gene expression was higher in mucinous rectal cancers compared to non-mucinous rectal cancers, with a p value of 0.056." (PMID 35912268, 2022). "On the other hand, elevated phospho-MLKL levels have been detected in esophagus and colon cancer, suggesting a tumor-promoting role." (PMID 35422482, 2022). "Patients with low MLKL levels in pancreatic adenocarcinoma, colon cancer, gastric cancer, cervical cancer, and ovarian cancer apparently have worsened overall survival." (PMID 35422482, 2022). "Decreased expression of MLKL has been found in many kinds of tumors, such as colon cancer, ovarian cancer, cervical squamous cell cancer, pancreatic adenocarcinoma and gastric cancer." (PMID 30005626, 2018). "Abnormal expression of MLKL has been detected in many kinds of tumors, such as breast cancer, colon cancer, ovarian cancer and gastric cancer." (PMID 30005626, 2018). "In order to do this, we used immunohistochemistry to determine the levels of phosphorylated MLKL (pMLKL) in pre-treatment biopsy samples from a cohort of human esophagus cancer patients and a cohort of human colon cancer patients." (PMID 26959742, 2016). "While CaMKII-mediated MLKL phosphorylation executes necroptosis in colon cancer cells treated with OSW-1 and smooth muscle cells treated with TNF-α plus z-VAD, it was found to facilitate autophagic flux and protect cells from starvation-induced death in L929 mouse fibroblast cells." (PMID 40329104, 2025). "In addition, low expression of MLKL is related to decreased overall survival in colon cancer patients after surgery." (PMID 36238158, 2022). "Finally, MLKL can also activate cell-surface proteases (ADAM family) that in their turn promote invasion of colon cancer cells." (PMID 35422482, 2022). "Abnormal expression of MLKL has been detected in many kinds of tumors, such as colon cancer, ovarian cancer, and gastric cancer and recent studies also have revealed that MLKL could serve as a potential prognostic biomarker for patients with cancer." (PMID 32917855, 2020). "In addition, the expression of MLKL was also found decreased in multiple tumor tissues including ovarian carcinoma, gastric cancer, colon cancers, and so on." (PMID 33643911, 2020). "Moreover, the reduced level of MLKL was markedly correlated with the reduced OS in gastric cancer, ovarian carcinoma, cervical squamous cell carcinoma and colon cancers, probably because MLKL can affect the modulation of local tumor microenvironment immunosurveillance." (PMID 31122251, 2019).
colon carcinoma (continued). "In this context, Sun and colleagues utilized liposomes for the simultaneous delivery of MLKL plasmid DNA, zVAD (a pan-caspase inhibitor peptide) and second mitochondria-derived activator of caspase (SMAC) to induce necroptosis in colon cancer cells." (PMID 40691738, 2025). "The same effect was observed in another cell line, human colon cancer HT-29 cells, which express endogenous RIPK3 and MLKL." (PMID 34862394, 2021). "HT29 colon cancer cells are widely used to detect necroptosis by co-treatment with TNFα, BV6 (IAP inhibitor) and z-VAD-fmk (caspase inhibitor), and MLKL (mixed lineage kinase domain like pseudokinase) phosphorylation is used as a marker of necroptosis." (PMID 32354117, 2020). "We previously reported that CRISPR/Cas9-mediated knockout (KO) of USP22 in the human colon carcinoma cell line HT-29 affects RIPK3 ubiquitination during necroptosis without inducing major changes in RIPK1, RIPK3, and MLKL gene expression, suggesting gene-specific regulation of USP22." (PMID 35933402, 2022).